CTHRC1 (collagen triple helix repeat containing 1)
Diseases named in the same sentence as CTHRC1 in open-access papers (continued):
Sharing a sentence is not in itself a finding about the gene and the disease.
melanoma (continued). "Furthermore, CTHRC1 may be a useful marker for primary melanoma and BRMS1 serves an important marker for metastatic melanoma distinguishing from dysplastic nevi." (PMID 23028750, 2012). "CD274, PDCD1, CTLA4, and LAG3 were significantly positively correlated with CTHRC1 expression in colon cancer and thyroid cancer; while only CTLA4 was significantly positively correlated with CTHRC1 expression in melanoma." (PMID 39052013, 2024). "In summary, this study demonstrated that CTHRC1 was correlated with BRAF(V600E), prognosis, and clinicopathological features in colon cancer, thyroid cancer, and melanoma." (PMID 39052013, 2024). "Further, P4HA1 knockdown reduced the secretion of collagen triple helix repeat containing 1 (CTHRC1), an important mediator of melanoma cell migration and invasion, in vitro and its deposition around tumor blood vessels in vivo." (PMID 32053263, 2020). "CTHRC1 was also highly upregulated in WM239 and WM793 melanoma cell lines compared to normal melanocytes." (PMID 32053263, 2020). "We also show that prolyl 4‐hydroxylase function is essential for the secretion of collagen triple helix repeat containing 1 (CTHRC1), an important mediator of melanoma cell migration and invasion." (PMID 32053263, 2020). "Treatment with DHB increased the amount of intracellular CTHRC1 and reduced CTHRC1 secretion in WM239 as well as in SKMEL‐28 melanoma cells." (PMID 32053263, 2020). "Among the most interesting, highly and significantly over-expressed genes in metastatic primary melanomas were TIMP1, VCAN, SPP1, and CTHRC1, all of which are expressed both by stromal fibroblasts and melanoma cells (data not shown)." (PMID 26918341, 2016). "Our analyses of the established melanoma cell lines from VGP primary melanomas (WM115 and WM793) and melanoma metastases (WM239, MM170, SKMEL-28, SKMEL-103, SKMEL-147, and BLM) revealed that they expressed variable levels of CTHRC1 mRNA." (PMID 26918341, 2016). "Interestingly, the genes coordinately expressed with CTHRC1, i.e. ITGB3, NFAT, and FN1, have all been implicated in angiogenesis, suggesting that these molecules may be associated with the increased angiogenesis and blood vessel density detected in melanomas." (PMID 26918341, 2016). "Immunohistochemical expressions of 12 promising biomarkers (pAkt, Bim, BRG1, BRMS1, CTHRC1, Cul1, ING4, MCL1, NQO1, SKP2, SNF5 and SOX4) were studied in 122 melanomas and 33 dysplastic nevi on tissue microarrays." (PMID 23028750, 2012). "Moreover, we examined the correlation between CTHRC1 expression and immunotherapy markers, including CD274, PDCD1, CTLA4, and LAG3 in colon cancer, thyroid cancer, and melanoma." (PMID 39052013, 2024). "Several signaling pathways, immune cell infiltration, and immunotherapy markers were correlated with CTHRC1 expression in colon cancer and thyroid cancer, though not as significantly in melanoma." (PMID 39052013, 2024). "Interestingly, we found that CTHRC1 and FN1 mRNA expression correlated in primary melanocytes, nevus cells, and melanoma cells, as well as in melanoma cell lines and primary melanoma tissues." (PMID 26918341, 2016). "Furthermore, since oncogenic BRAF has been found to activate NFAT signaling in melanoma, and we found that CTHRC1 is expressed at high levels mainly in BRAF mutant melanoma cell lines, we examined the effect of BRAF inhibition on CTHRC1 expression." (PMID 26918341, 2016). "Since CTHRC1 overexpression has been found to enhance cell adhesion and migration, we tested the adhesion of melanoma cells (WM793, WM239, and MM170) and adult human fibroblasts on surfaces coated with the recombinant full-length CTHRC1 protein produced in human cells." (PMID 26918341, 2016). "The cells from primary and metastatic melanomas showed a variable but higher (46-fold) CTHRC1 expression than normal melanocytes or benign nevus cells, in which CTHRC1 expression was virtually absent." (PMID 26918341, 2016).
melanoma (continued). "Further, we have found CTHRC1 to be expressed in lymph node macrometastases at a similar high level to that in primary melanomas (and data not shown)." (PMID 26918341, 2016). "CTHRC1 was found to be expressed in 16 out of 19 types of human solid tumors including invasive melanoma but not in benign nevus and non-invasive melanoma." (PMID 23922981, 2013). "CTHRC1 inhibitors could potentially be used as adjuvant treatment alongside BRAF(V600E)-targeted drugs in BRAF(V600E) mutant colon cancer, thyroid cancer, and melanoma." (PMID 39052013, 2024). "Based on database analysis and clinical tissue studies, CTHRC1 was verified to correlate with poor prognosis and worse clinicopathological features in colon cancer and thyroid cancer patients, but not in patients with melanoma." (PMID 39052013, 2024). "CTHRC1 is another interesting gene significantly overexpressed in primary melanomas compared to benign nevi (4.1-fold) and in metastatic compared to non-metastatic primary melanomas (2.4-fold)." (PMID 26918341, 2016). "Therefore, our data indicated that CTHRC1 expression was significantly correlated with multiple types of immune cell infiltration and immunotherapy marker expression in colon cancer and thyroid cancer, but not as significantly in melanoma." (PMID 39052013, 2024). "Since we found that CTHRC1 is coordinately expressed with the transcription factor NFATC2 in melanoma cell lines, and the NFATC2 protein has been found to be expressed by melanoma cells in vitro and in vivo, we studied whether NFATC2 induces the expression of CTHRC1." (PMID 26918341, 2016).
myocardial infarction (18 papers, 2020 to 2026). Gross necrosis of the myocardium, as a result of interruption of the blood supply to the area, as in coronary thrombosis. "Previous studies in the heart have revealed that the deletion of Cthrc1 resulted in ventricular rupture and significant loss of the “collagen scaffold” that is necessary for proper repair after myocardial infarction." (PMID 39836476, 2025). "In one report, both Cthrc1 and Sox9 gene expression were significantly upregulated in a subpopulation of activated, pro-fibrotic fibroblasts following myocardial infarction in mice." (PMID 40076432, 2025). "For example, studies have revealed the key role of CTHRC1 in collagen deposition after myocardial infarction by single-cell sequencing." (PMID 40166462, 2025). "Cthrc1 knockout mice showed a dramatically poorer survival rate after myocardial infarction (80% wildtype versus 30% knockout) due to ventricular rupture as a result of decreased collagen deposition." (PMID 37421484, 2024). "scRNA-seq analysis revealed a crucial role for collagen triple helix repeat containing 1 as a novel regulator of myocardial infarction scar healing via cardiac fibroblasts after myocardial infarction." (PMID 39224111, 2024). "Cthrc1 was down-regulated during the myocardial infarction recovery period to avoid pathological ventricular remodeling." (PMID 35958408, 2022). "In addition, TGFβ1-SMAD2/3 signaling can improve cardiac repair after myocardial infarction by inducing myocardial fibroblasts to express CTHRC1 and then selectively activate WNT5A signialing pathway." (PMID 37284318, 2023). "However, CTHRC1-positive CF have been identified in scars of hearts of mouse and swine models of myocardial infarction (MI), as well as, in human samples from cardiovascular disease patients." (PMID 36531712, 2022). "Studies on myocardial infarction (MI) have also found that activation of infarct repair cardiac fibroblasts (IRCF) involves CTHRC1 expression and PI3K-Akt signaling pathway." (PMID 32848510, 2020). "It has been shown that a subpopulation of activated fibroblasts in heart tissue co-express high levels of CTHRC1 and SOX9 following myocardial infarction." (PMID 40076432, 2025). "In a study focused specifically on the role of active fibroblasts in myocardial infarction in mice, a subpopulation called cells reparative cardiac fibroblasts (CFRs), was identified by the expression of POSTN and collagen triple helix repeat containing 1 (CTHRC1)." (PMID 35548426, 2022).
ovarian carcinoma (18 papers, 2014 to 2025). A malignant neoplasm originating from the surface ovarian epithelium. "Ovarian cancer cells secrete CTHRC1, which activates STAT6 signaling in TAMs, inducing their M2 polarization." (PMID 40963633, 2025). "In ovarian cancer tissues, CTHRC1 is overexpressed, especially in advanced-stage tumors, and is strongly correlated with increased infiltration of M2-like TAMs, which are known to facilitate tumor growth and metastasis." (PMID 40330466, 2025). "In epithelial ovarian cancer, overexpression of CTHRC1 promotes EMT, thereby enhancing tumor invasion and metastasis, a mechanism also implicated in lung, gastrointestinal, breast, and pancreatic cancers." (PMID 40963633, 2025). "Overexpression of miR-30b-3p in ovarian cancer cells inhibited cell migration and invasion by targeting CTHRC1 that plays an important role in epithelial–mesenchymal transition." (PMID 38256218, 2024). "CTHRC1 is a cancer-related gene involved in certain signaling molecules' phosphorylation, enhancing the migration and invasion of ovarian cancer." (PMID 33859913, 2021). "Then, our analysis showed that CTHRC1 protein, localized in the nucleus, was also increased in certain tumors, such as ovarian cancer, UCEC, etc.." (PMID 34702252, 2021). "Mir-30b-3p can regulate the expression of EMT-related proteins and prevent the development of EMT in ovarian cancer cells by targeting and inhibiting the expression of CTHRC1." (PMID 32156314, 2020). "Related to matrix component effects, the upregulation of collagen triple helix repeat containing-1 by ovarian cancer cells was shown to trigger metastasis of ovarian cancer via an integrin β3/FAK signaling pathway." (PMID 31779287, 2019). "We further analyzed the protein expression and clinical significance of CTHRC1 in 72 ovarian cancer tissue samples obtained from patients by IHC." (PMID 29021002, 2017). "To investigate the expression of CTHRC1 in human ovarian cancer tissue, we first examined the mRNA levels of Cthrc1 in 10 normal ovarian samples, and 15 epithelial ovarian cancer tissues using real time RT-PCR analysis." (PMID 29021002, 2017). "To define the predictive role of CTHRC1 expression in ovarian cancer metastasis, we performed Logistic regression analysis." (PMID 29021002, 2017). "The correlation between CTHRC1 and integrin β3/FAK signaling exposes the mechanisms underlying peritoneal ovarian tumor dissemination, and provides a new direction in ovarian cancer diagnosis and treatment." (PMID 29021002, 2017). "Simultaneously, the increasing expression of integrin β3 was observed with the progress of ovarian cancer too, and statistical analysis revealed a strong correlation between CTHRC1/integrin β3 co-expression (P = 0.001) and tumor metastasis." (PMID 29021002, 2017). "Although the function of CTHRC1 in ovarian cancer cell metastasis is well-known, the mechanisms remained unclear." (PMID 29021002, 2017). "Both CTHRC1 and integrin β3 are good candidate markers for predicting progression and prognosis of ovarian cancer." (PMID 29021002, 2017). "In our study, we first used comparative proteomic analysis to verify the aberrant expression of CTHRC1 in ovarian cancer tissues compared with benign ovarian tissues." (PMID 26452130, 2015). "CTHRC1 overexpression induced ovarian cancer cell lines to undergo EMT and promoted cell migration and invasion through activating Wnt/β-catenin signaling, making CTHRC1 a potential target for EOC treatment." (PMID 26452130, 2015). "Indeed, increased CTHRC1 expression in epithelial ovarian cancer cells induces epithelial–mesenchymal transition, thereby promoting tumor cell invasion and metastasis." (PMID 38256218, 2024). "Similarly, high CTHRC1 expression was implicated in a shorter OS (P < 0.0001), PFS (P < 0.0001) and PPS (P = 0.00049) of patients with ovarian cancer." (PMID 34702252, 2021).
ovarian carcinoma (continued). "We analyzed the effect of mir-30b-3p on the proliferation, cell cycle, migration and invasion of ovarian cancer cells, and investigated whether this effect was related to the CTHRC1." (PMID 32156314, 2020). "Moreover, we demonstrated that CTHRC1 interacts with integrin β3 physically, which furthermore attests the mechanism of CTHRC1 in ovarian cancer cell." (PMID 29021002, 2017). "Here we examined whether stable over-expression of CTHRC1 increases EOC cell intraperitoneal dissemination in an in vivo ovarian cancer model." (PMID 29021002, 2017). "In addition, univariate and multivariate logistic regression analysis suggested that CTHRC1 is an independent influential factor for ovarian cancer metastasis." (PMID 29021002, 2017). "Also, our IHC assessment of ovarian cancer from patients and xenograft tumor tissues showed a strong correlation between the co-expression of CTHRC1 and integrin β3 as the tumor progression." (PMID 29021002, 2017). "Furthermore, we established a set of human ovarian cancer cell lines in which CTHRC1 was stably up- or down- regulated." (PMID 29021002, 2017). "Furthermore, in parallel with over-expression of integrin β3, CTHRC1 was significantly up-regulated in ovarian cancer tissue, and positively correlated with the FIGO stage, peritoneal metastasis status and lymph node metastasis." (PMID 29021002, 2017). "We made a further confirmation that CTHRC1 could promote ovarian cancer cells migration and invasion by activating the integrin β3/FAK signaling." (PMID 29021002, 2017). "Notably, CTHRC1 has recently been reported to promote invasion and metastasis of ovarian carcinoma cells in xenograft assays." (PMID 26918341, 2016). "This indicates that CTHRC1 not only recruits macrophages but also reprograms them into an immunosuppressive M2 state, which supports cancer metastasis, making CTHRC1 a potential therapeutic target for disrupting this pro-tumorigenic interaction in ovarian cancer." (PMID 40330466, 2025). "Consequently, integrin β3 blocking antibody MAB1957 and the FAK inhibitor PF-228 were used to verify whether the inhibition of integrin β3 function and FAK phosphorylation would restore the influence of CTHRC1 on ovarian cancer cell migration and invasion." (PMID 29021002, 2017). "However, the expression characteristics and function of CTHRC1 in epithelial ovarian cancer (EOC) remain unclear." (PMID 26452130, 2015). "Collagen triple helix repeat containing 1(CTHRC1), secreted by epithelial ovarian Cancer (EOC) cells, promoted M2-like polarization of tumor-associated macrophages (TAMs) by activating STAT6." (PMID 36524006, 2022). "CTHRC1 was also found to be increasing the expression of Integrinβ3 and phosphorylating focal adhesion kinase (FAK), which led to invasion and migration of ovarian cancer cells, enhanced adhesion to ECM proteins, peritoneal and lymph node metastasis." (PMID 33859913, 2021). "The results indicated that miR-30b-3p increased the expression of E-cadherin and β-catenin by targeting CTHRC1 and ultimately inhibited the EMT process in ovarian cancer cells." (PMID 32156314, 2020). "MiR-30b-3p targets CTHRC1 gene plays an important role in epithelial–mesenchymal transformation (EMT), and supports miR-30b-3p as a potential biological indicator for ovarian cancer in the future." (PMID 32156314, 2020). "It was recently demonstrated that EGFR inhibitors attenuated the promoting effect of CTHRC1 on epithelial ovarian cancer invasion and that phosphorylation of EGFR and ERK1/2 was reduced in CTHRC1-silenced ovarian cancer cells." (PMID 28645305, 2017). "For example, many TGF-β signaling-related genes derived from CAFs play important roles in the crosstalk between fibroblasts and ovarian cancer, including periostin (POSTN), collagen type XI alpha 1 (COL11A1), collagen triple helix repeat containing-1 (CTHRC1), and versican (VCAN)." (PMID 35681617, 2022).
ovarian carcinoma (continued). "Hence it was suggested that CTHRC1, by activating EGFR signaling, promotes metastasis in ovarian cancer, which is mediated through ERK1/2, PI3K/AKT." (PMID 33859913, 2021). "However, the overexpression of CTHRC1 leads to the upregulation of integrin β3 in model mice, proving that CTHRC1 interacts with integrin β3 and promotes FAK phosphorylation at Tyr397, thereby promoting ovarian cancer cell adhesion, migration, and invasion." (PMID 32848510, 2020). "The lowest expression of CTHRC1 in ovarian cancer cell lines was observed in HO8910 cells, which was therefore stably transfected with Lenti-CTHRC1, thus obtaining the CTHRC1-overexpressing cell line, HO8910-CTHRC1." (PMID 29021002, 2017). "In ovarian cancer cells, gene silencing CTHRC1 does not alter MMP9 expression or phosphorylate MEK." (PMID 32848510, 2020). "Our results suggest that CTHRC1, a newly identified regulator of i.p. metastasis through activation of integrin β3/FAK signaling in EOC, may represent a potential therapeutic target for ovarian cancer." (PMID 29021002, 2017).